CRP (C-reactive protein)
Diseases named in the same sentence as CRP in open-access papers (continued):
Sharing a sentence is not in itself a finding about the gene and the disease.
vasculitis (continued). "CRP, an acute phase protein, increases with systemic inflammation in vasculitis." (PMID 40210775, 2025). "However, CRP remained persistently elevated, and this was likely due to the ongoing systemic inflammation from large vessel vasculitis." (PMID 40994759, 2025). "Disease-specific factors, as pointed out by the Birmingham Vasculitis Activity Score and C-reactive protein levels, might indicate an intense systemic inflammation as a particular contributor to accelerating the atherosclerotic processes." (PMID 39857028, 2025). "We included several baseline factors that potentially might influence relapses such as vasculitis activity, inflammatory status as measured by CRP and organ involvement, in a Cox proportional hazard model." (PMID 39718586, 2024). "An inflammatory origin was considered if the patient presented with an elevation of one of the biological inflammatory markers (ESR, CRP, fibrinogen or abnormal plasma protein electrophoresis) and/or vasculitis or papillitis diagnosed on FA and detected in 11 patients (21.1%)." (PMID 37601780, 2023). "Compared to survivors, the death group exhibited a higher smoking index, lower serum albumin levels, higher serum C-reactive protein levels, higher Birmingham Vasculitis Activity Score (BVAS), higher Five-Factor Score, and a more severe European Vasculitis Study Group (EUVAS) categorization system." (PMID 37986108, 2023). "Clinical factors such as BVAS, vasculitis damage index, CRP and BMI were also collected." (PMID 36890852, 2023). "Among the patients with MPA, those with motor neuropathy had significantly higher total Birmingham Vasculitis Activity Scores and serum levels of C-reactive protein (CRP), tissue inhibitor of metalloproteinase-1 (TIMP-1), and interleukin-6 than patients without motor neuropathy." (PMID 36362162, 2022). "CRP levels greater than 8mg/mL are considered elevated, and a statistically significant elevation was noted in patients with transverse myelitis (p value 0.046) and vasculitis (p- value 0.011)." (PMID 34679418, 2021). "CRP levels can reach very high levels in autoinflammatory diseases such as vasculitis and systemic juvenile idiopathic arthritis, while leukocyte count may be normal or only moderately elevated." (PMID 32030452, 2020). "Compared to patients without PN, patients with PN had a higher erythrocyte sedimentation rate, C-reactive protein, rheumatoid factor, Birmingham vasculitis activity score (BVAS), and positivity of myeloperoxidase-antineutrophil cytoplasmic antibodies (MPO-ANCA)." (PMID 32714994, 2020). "Erythrocyte sedimentation rate (ESR) and C-reactive protein (CRP), the most common laboratory signs of inflammation in general, are usually considered being helpful in identifying active vasculitis, especially in untreated patients, or ruling out this kind of disease." (PMID 31244756, 2019). "Similarly measuring CRP levels is helpful in monitoring disease activity of various forms of vasculitis." (PMID 24167754, 2013). "Vasculitis: significant collagen vascular disease, giant cell arteritis, vasculitis, systemic necrotizing vasculitis (history, physical examination, erythrocyte sedimentation rate, C-reactive protein, antinuclear antibodies)." (PMID 21356042, 2011). "MLR analysis of sRAGE levels confirmed the negative associations with RAGE 82Ser, history of vasculitis, and with serum levels of CRP and HDL (P < 0.05)." (PMID 19284577, 2009). "Blood tests identifying signs of inflammation, such as elevated C-reactive protein (CRP) and erythrocyte sedimentation rate (ESR), and specific antibodies like ANCA (anti-neutrophil cytoplasmic antibodies), which are associated with certain types of vasculitis should be performed." (PMID 40673965, 2025).
vasculitis (continued). "Furthermore, all routine laboratory tests related to vasculitis, including erythrocyte sedimentation rate, C-reactive protein (CRP), blood count, serum creatinine, urinalysis, specific autoantibodies, complement, immunoglobulin, cryoglobulin, and hepatitis B and C serology, were negative." (PMID 40852359, 2025). "Notably, our previous study demonstrated a positive correlation between Sema4D and CRP levels and Z-score in KD, suggesting that molecules from the Sema family may serve as progression markers in the development of KD vasculitis." (PMID 38678170, 2024). "C- reactive protein (CRP) is an acute phase reaction protein, produced by the liver and triggered especially by interleukin-6 (IL-6) which is often used in the clinic as an inflammatory marker in “classical” inflammatory disease such as infections, vasculitis, tumors." (PMID 29467655, 2018). "Also normal levels of sedimentation rates and CRP made the vasculitis diagnosis less possible." (PMID 25580327, 2014). "CRP and MPO-ANCA were selected as covariates based on previous reports indicating that they reflect disease activity in vasculitis and influence renal prognosis." (PMID 40136450, 2025). "The Birmingham Vasculitis Score 2003 (BVAS) was used for assessment of disease activity and C-reactive protein (CRP), creatinine, albuminuria, and serum (s) and urinary (u) TWEAK levels were measured at baseline and 6-month follow-up." (PMID 40443963, 2025). "The following investigations were ordered: a chest radiograph, full blood count, urine and electrolytes, C-reactive protein (CRP), vasculitis screen, and connective tissue antibody screen." (PMID 39640133, 2024). "This patient also showed lower levels of MPO-ANCA, Birmingham Vasculitis Activity Score (BVAS), and C-reactive protein." (PMID 38873394, 2024). "For example, Kawasaki disease (KD), another vasculitis predominantly affecting infants and children younger than 5 years old, manifests as persistent fever and characteristic changes in the skin, mucous membrane, and lymph nodes with elevated CRP and ESR, which may also present in TAK patients." (PMID 38357518, 2024). "These drawbacks highlight the need for more convenient and objective biomarkers that can accurately reflect vasculitis activity and inflammation, such as those measured by BVAS, erythrocyte sedimentation rate (ESR), and C-reactive protein (CRP)." (PMID 39459426, 2024). "The Birmingham Vasculitis Activity Score (BVAS), the Five-Factor Score (FFS), erythrocyte sedimentation rate (ESR) and C-reactive protein (CRP) at diagnosis were assessed." (PMID 38102670, 2023). "Serum levels of C-reactive protein (CRP) and erythrocyte sedimentation rate (ESR) are reliable biomarkers for assessing vascular inflammation in large vasculitis and are employed in the current criteria to evaluate disease activity." (PMID 37215715, 2023). "Vasculitis, an autoimmune chronic inflammatory disease, is characterized by elevated levels of acute-phase proteins, including SAA and CRP, similar to other inflammatory disorders." (PMID 37026007, 2023). "Genetic testing and/or ADA2 activity detection should be considered in all patients with recurrent fever accompanied unexplained elevated CRP and/or ESR, especially in those with livedo racemosa/reticularis and evidence of PAN-like vasculitis." (PMID 36807221, 2023). "The correlation analysis showed a significant positive correlation between serum anti-LAMP-2 antibody levels and the Birmingham Vasculitis Activity Score (BVAS) and hypersensitive C-reactive protein (Hs-CRP) (all P < 0.05)." (PMID 35356030, 2022). "In contrast to CRP, PTX3 is produced at the site of inflammation, and high levels have been found in various forms of vasculitis and in atherosclerotic abdominal aorta." (PMID 36606286, 2022).
vasculitis (continued). "Patients with positive MPO-ANCA had higher levels of erythrocyte sedimentation rate (ESR), C-reactive protein, Birmingham Vasculitis Activity Score (BVAS), higher ratios of fever, myalgia, renal involvement, and biopsy-proven vasculitis." (PMID 35833130, 2022). "During the most recent admission, septic and vasculitis screens, including ESR and C-reactive protein, were normal." (PMID 34681037, 2021). "Important laboratory investigations, other than baseline laboratory investigations, include elevated inflammatory markers such as C-reactive protein (CRP), Erythrocyte Sedimentation Rate (ESR), high sensitivity troponin assay and an extended vasculitis panel." (PMID 33407141, 2021). "CRP, ESR, fibrinogen, d-dimers, albumin and hemoglobin in the peripheral blood correlate well with the activity of vasculitis and identify severe patients." (PMID 34445984, 2021). "The optimum cut-off levels for the disease activity of vasculitis were identified from the ROC curves for the WBC count (> 7250/mm3), serum CRP level (> 0.72 mg/dL), and serum 20S-proteasome level (> 563.1 ng/mL)." (PMID 32864569, 2020). "We found a significant correlation between higher CRP value and 18F-FDG-PET/CT positivity in patients diagnosed with vasculitis." (PMID 31531005, 2019). "Endothelial microvesicle levels in pediatric vasculitis correlated with the Birmingham Vasculitis Activity Score (BVAS), C-reactive protein, and erythrocyte sedimentation rate." (PMID 29181712, 2019). "We found that in patients with confirmed vasculitis diagnosis, 18F-FDG-PET/CT positivity was significantly related to a lower dose and shorter duration of GC medication and a higher CRP level." (PMID 31531005, 2019). "First, in terms of vasculitis activity of AAV, we conclude that lymphocyte count and NLR are significantly correlated with BVAS, comparable to ESR and CRP." (PMID 30064369, 2018). "The CRP and ESR levels returned to the normal range, suggesting that the activity of the vasculitis was controlled." (PMID 27175653, 2016). "When diagnosed, the levels of CRP and ESR, which were tested to determine the activity of vasculitis, were higher than the normal range." (PMID 27175653, 2016). "Screening for infections and vasculitis including anti-nuclear antibodies (ANA), anti-neutrophil cytoplasmic antibodies, erythrocyte sedimentation rate (ESR), c-reactive protein (CRP) were normal." (PMID 25888897, 2015). "The criteria for exclusion from the database were 1) serum C-reactive protein (CRP) > 3 mg/dL, 2) WBC count > 9,000/mm3 or <4,000/mm3, and 3) patients with cancer, immune complex disease, or vasculitis." (PMID 22583484, 2012). "Furthermore, all routine laboratory tests related to vasculitis, such as EST, CRP, blood count, serum creatinine, urinalysis, specific autoantibodies, complement, immunoglobulin, cryoglobulin, and hepatitis B and C serology, were negative." (PMID 40852359, 2025). "CRP, one of the markers of inflammation, is used to rule out vasculitis and is markedly elevated with active disease." (PMID 40385871, 2025). "Erythrocyte sedimentation rate (ESR) and C-reactive protein (CRP) levels were collected as indices reflecting cross-sectional comprehensive inflammation, whereas the Birmingham vasculitis activity score (bVAS), and the five-factor score (FFS) were reviewed as AAV-specific indices." (PMID 39064611, 2024). "The variables at AAV diagnosis such as demographic data, AAV-specific data including the Birmingham vasculitis activity score (BVAS), five-factor score (FFS), and laboratory data including ANCA, erythrocyte sedimentation rate (ESR), and C-reactive protein (CRP) were collected." (PMID 37373863, 2023). "The phenotype of this early vasculitis is related to an increase in complement consumption without an elevated CRP in the serum." (PMID 37711763, 2023).
vasculitis (continued). "Overall C-reactive protein (CRP) was 4.9 mg/l (range, 0.02–28.21 mg/l), nonsignificantly differing between the vasculitis and non-vasculitis group (5.27 vs. 4.49 mg/l; p > 0.05)." (PMID 36262692, 2022). "In contrast to CSF analysis, we found inflammation markers in the blood, i.e. elevated ESR and CRP, vasculitis parameters, and oligoclonal bands to be negative in most cases of RCVS." (PMID 35227319, 2022). "Thus, the effect of systemic inflammation due to the vasculitis itself may have a synergic impact on cardiovascular risk in addition to CVRFs, leading to premature atherosclerosis, as suggested by our results with a significant association between MACE occurrences and higher CRP levels." (PMID 34070514, 2021). "Though CRP has been known to reflect the extent of systemic inflammation and vasculitis, it alone does not always reflect the severity of KD or the treatment response of IVIG." (PMID 34530763, 2021). "We next assessed whether concentrations of LAMP-2-ANCA correlated with standard clinical measures of disease activity, namely, C-reactive protein (CRP, mg/L), erythrocyte sedimentation rate (ESR, mm/hr), and pediatric vasculitis activity score (pVAS)." (PMID 33613565, 2020). "Vasculitis patients with a positive 18F-FDG-PET/CT result had significantly higher C-reactive protein (CRP) than patients with a negative 18F-FDG-PET/CT finding (mean value = 154.5 vs 90.4 mg/L, p=0.018)." (PMID 31531005, 2019). "Vasculitis patients with a positive 18F-FDG-PET/CT scan had significantly higher CRP values than vasculitis patients with a negative 18F-FDG-PET/CT scan (mean CRP = 154.5 mg/L; SD 100.2 mg/L vs 90.4 mg/L; SD 55.6 mg/L, respectively; p=0.018)." (PMID 31531005, 2019). "Specific diagnostic tools routinely employed included the following: ESR or CRP (Rheum 75.8%, Neph 50%, p=0.0019), ANCA titer (63.0%, p=0.1473), hematuria and/or proteinuria (73.9%, p=0.1038), and 9.4% (p=0.4970) use the Birmingham Vasculitis Activity Score." (PMID 30155302, 2018). "Use of such measures in tracking vasculitis-related inflammation in adults beyond diagnosis is generally considered controversial, in part because ESR and CRP are affected by renal function, high dose corticosteroids, concurrent infections and other co-morbidities." (PMID 30533405, 2018). "Furthermore, higher ESR, CRP, and TNF-α titers, the occurrence of RA vasculitis, and RA lung disease emerged as strong disease-specific predictors of cardiovascular mortality." (PMID 23209899, 2012). "Moreover, the levels of serum NGAL in patients with vasculitis, had a closer correlation with clinical findings (Birmingham Vasculitis Activity Score, BVAS) than erythrocyte sedimentation rate, C-reactive protein, and anti-neutrophil cytoplasmic antibody did." (PMID 20680102, 2010). "Simple linear regression analysis showed that serum sRAGE levels in RA patients were negatively associated with current smoking, family history of CV disease, history of vasculitis, diastolic blood pressure, RF, carriage of RAGE 82Ser, and serum levels of CRP and S100A8 (P < 0.05)." (PMID 19284577, 2009). "Increased ESR or CRP is nonspecific and present in infection and vasculitis conditions." (PMID 39036250, 2024). "While elevated baseline CRP at disease onset of AAV has already been described as a determinant of poor long-term outcomes, its clinical implications at disease onset of AAV with respect to vasculitis manifestations and complement system activation remain elusive." (PMID 36834488, 2023). "In addition, patients with IgAN generally do not experience vasculitis apart from in the kidney, and none in this study exhibited findings indicating SV, such as fever, abdominal pain, and high serum CRP level." (PMID 38111574, 2023).
vasculitis (continued). "In addition, normal CRP levels and lack of response to corticosteroids also make inflammatory vasculopathy (i.e., vasculitis, such as Takayasu or polyarteritis nodosa) less likely, although a mural contrast enhancement was observed in some patients." (PMID 35795628, 2022). "The fact that some patients with remission PR3- and MPO-AAV, despite a Birmingham Vasculitis Activity Score Version 3 (BVAS) of 0, still had slightly elevated CRP levels and persistent low-titer ANCAs suggests that some residual inflammation may explain this observation." (PMID 36125911, 2022). "Additionally, an association of anti-tubulin-α-1c with deep venous thrombosis and erythema nodosum, and a significant correlation with the extent of inflammatory processes in BD and indicators of disease activity, such as ESR, CRP and BVAS (Birmingham Vasculitis Activity Score) were found." (PMID 31244756, 2019). "In EGPA, the frequency of renal involvement, serum CRP levels, and Birmingham Vasculitis Activity Score (BVAS) in the aLf-positive patients was significantly higher than those in the aLf-negative patients, and the aLf titer correlated positively with the serum CRP level and BVAS." (PMID 28066444, 2016). "Despite significant vascular stenosis, the absence of elevated inflammatory markers (ESR, CRP), constitutional symptoms, or other organ-threatening manifestations suggested a chronic, immunologically mediated vasculopathy rather than an acute, destructive vasculitis." (PMID 41293154, 2025). "During vasculitis, whether ANCA positive or not, PEVs are increased and are associated with active disease, inflammation (immune cell counts, erythrocyte sedimentation rate (ESR), C-reactive protein (CRP)), and renal damage." (PMID 35887184, 2022). "The biomarkers ESR and CRP will be raised, but they are not specific, whereas ANCA is specific and useful in ruling out vasculitis." (PMID 39429722, 2024). "The plasma level of mCRP was correlated with Birmingham vasculitis activity score (BVAS), eGFR, BNP, EF%, LVEDV, LVESV, LVMI, and STEMI complications’ Gensini score in AAV; however, CRP did not correlate with BNP, EF%, LVEDV, LVESV, LVMI, and Gensini score." (PMID 33008437, 2020). "Current practice relies on general and unspecific inflammation parameters, such as erythrocyte sedimentation rate (ESR) and C-reactive protein (CRP), that do not correlate well with disease activity in vasculitis." (PMID 30704507, 2019). "Both BVAS and PVAS are based on the assessment of clinical features of vasculitis and do not consider routine laboratory markers of inflammation, such as erythrocyte sedimentation rate (ESR) and C-reactive protein (CRP)." (PMID 30533405, 2018). "Thrombophilia and vasculitis markers (ESR, CRP, and ANCA) were negative." (PMID 39429722, 2024). "In clinical practice, some patients may undergo deterioration of vasculitis without elevation of CRP or ESR, and increases in CRP or ESR are found in only approximately half of patients with active TA." (PMID 33778164, 2021). "However, due to the heterogeneity of clinical manifestations, unclearness of the pathogenesis and the traditional biomarker like CRP (C-reactive protein), ESR (erythrocyte sedimentation rate), interleukin family, or imaging examinations failed to diagnose and evaluate the vasculitis timely." (PMID 33997033, 2021).